AKR1C3 (aldo-keto reductase family 1 member C3)
Diseases named in the same sentence as AKR1C3 in open-access papers (continued):
Sharing a sentence is not in itself a finding about the gene and the disease.
tumor (continued). "The analysis of the expression of AKR1C3 and related proteins and the analysis of the tumor immune microenvironment provide ideas for immunotherapy and related drug research and development." (PMID 36901944, 2023). "The present study revealed that AKR1C3 promotes the proliferation and colony formation of some human HCC cells in vitro and that AKR1C3 is important for tumor growth in nude mice." (PMID 38188684, 2023). "Increasing evidence indicates that AKR1C3 expression is a prognostic factor for tumor progression and drug resistance in a variety of malignancies." (PMID 35359392, 2022). "AKR1C3 is highly expressed in a variety of tumor cells, promoting the occurrence and development of tumors by affecting angiogenesis and similar processes and is closely related to a poor prognosis." (PMID 35883650, 2022). "Selective AKR1C3 inhibitors were used to evaluate the effect of AKR1C3 inhibition on HCC tumor growth and induction of autophagy." (PMID 36451864, 2022). "Overexpression of AKR1C3 to eliminate reactive oxygen species (ROS) allows the continuous activation of the AKT pathway in tumor cells upregulated by AKR1C3, thereby reducing cell apoptosis." (PMID 35359392, 2022). "Inhibition of AKR1C3 enzymatic activity resulted in significant inhibition of enzalutamide-resistant tumor growth." (PMID 35359392, 2022). "As ROS and OS were demonstrated to have a strong effect on the expression of VEGF/VEGFR2, we performed immunohistochemical staining against NRF2 and AKR1C3 to prove the occurrence of OS in the tumor tissue." (PMID 34680369, 2021). "We confirm substantial expression of HSD11B2 and AKR1C3 in nearly all CRPC tumor samples (93% and 100%, respectively)." (PMID 33974560, 2021). "Previously, we evaluated AKR1C3 expression by immunohistochemistry in microarrays consisting of sections of human tumour or normal tissues." (PMID 34959631, 2021). "Further, the phosphate pre-prodrug of SN29176, termed SN35141, is refractory to AKR1C3 activation in vivo but retains promising efficacy in combination with radiotherapy in human tumour xenograft models." (PMID 34959631, 2021). "Together, this study showed a new mechanism by which the AKR1C3/AR‐V7 complex regulates CRPC tumour growth by repressing a novel tumour‐suppressor gene." (PMID 32902124, 2020). "The functions of the AR‐V7/AKR1C3 complex on tumour growth were further studied by using MTT and colony formation assays in vitro." (PMID 32902124, 2020). "AKR1C3 is an important enzyme in the steroidogenesis pathway that can produce androgen intratumorally to maintain CRPC tumour growth after ADT." (PMID 32902124, 2020). "Collectively, these data suggested that the AR‐V7 target gene B4GALT1, as a novel tumour suppressor in PCa, was negatively regulated by AR‐V7/AKR1C3 complex." (PMID 32902124, 2020). "Cell clone experiments confirmed AKR1C3 overexpressing DU145 cells are resistant to radiation, And Suppression of AKR1C3 via its chemical inhibitor indocin restored the sensitivity of the acquired tumor cells." (PMID 27385003, 2016). "Overall, the median level of AKR1C1, AKR1C2 and AKR1C3 was decreased in tumour, relative to normal tissue but when only mutant cases were considered, all AKRs were significantly increased." (PMID 27824809, 2016). "For example, AKR1C3 is also a prostaglandin F synthase and is involved in prostaglandin alterations that stimulate tumor growth, angiogenesis, and invasiveness." (PMID 24848372, 2014). "These tumor specimens were then screened via immunohistochemistry to determine the expression levels of AKR1C3." (PMID 25419901, 2014). "The remaining 5 (25%) had a low or undetectable levels of AKR1C3 expression (+/−, i.e. 0–50% tumor cells were AKR1C3 positive)." (PMID 25419901, 2014). "Only 3 (37%) of the radiosensitive tumor samples had intermediate levels of AKR1C3 but 5 (63%) showed a low or undetectable level (+/−) of AKR1C3 expression." (PMID 25419901, 2014).
tumor (continued). "Overexpression of cdk6 in tumor cell lines having low cdk6 resulted in decreased levels of mRNAs encoding aldo-keto reductase (AKR)1C1, AKR1C2 and AKR1C3, which are hydroxysteroid dehydrogenases (HSDs) involved in steroid hormone metabolism." (PMID 24848372, 2014). "Other groups have demonstrated that elevated expression of AKR1C3 can suppress differentiation of HL-60 tumor cells and promote angiogenesis of PC-3 tumor cells, both associated with a poor therapeutic outcome." (PMID 25419901, 2014). "Cytoplasmic AKR1C3 immunostaining was demonstrated in most tumor epithelial cells while nuclear staining was heterogeneously observed and not scored." (PMID 24244276, 2013). "In these ways, AKR1C3 contributes to tumour development and maintenance, and suggest that inhibition of AKR1C3 activity is an attractive target for the development of new anti-cancer therapies." (PMID 22937138, 2012). "PR-104 is a phosphate ester dinitrobenzamide mustard precursor of the prodrug PR-104A that is designed to become activated into cytotoxic nitrogen mustards in tumour regions that are either hypoxic or express AKR1C3." (PMID 23098625, 2012). "Here we propose a novel pathological function of AKR1C3 in tumor angiogenesis and its potential role in promoting PCa progression." (PMID 21134280, 2010). "The genes of the SLC family such as SLC2A14 and SLC2A3 and the AKR1 (aldo-keto reductase 1) family such as AKR1C1, AKR1C2, AKR1C3 and AKR1B10 were associated with the metabolic processes of tumor cells." (PMID 20003295, 2009). "Many studies have revealed the role of AKR1C3 in tumor progression." (PMID 40055914, 2025). "Furthermore, alterations in genes such as MYC, ERBB2, FGFR1, GATA3, and AKR1C3 in tumor cells signal their critical roles in the progression of early breast malignancies." (PMID 40489436, 2025). "Additionally, we further explored the public database GEO and found AKR1C3 was also upregulated in the tumor tissues compared to the adjacent normal tissues in EAC patients." (PMID 40603306, 2025). "In addition, AKR1C3 was found to induce chemoresistance by regulating redox balance and ROS production in malignant tumor cells." (PMID 40055914, 2025). "Additionally, AKR1C3 promotes tumor proliferation and invasion through the IL6/STAT3 pathway, as evidenced by gain- and loss-of-function experiments." (PMID 38523637, 2024). "AKR1C3 contributes to the accumulation of lipid droplets (LD) in HCC, a phenomenon associated with cancer metastasis, stem cell proliferation, and chemoresistance across various tumor types." (PMID 38523637, 2024). "Knockdown of AKR1C3 in Huh7 cells reduced tumor growth in vivo." (PMID 38188684, 2023). "Therefore, the inhibition of AKR1C3 expression and the attendant androgen synthesis in tumor cells can be used as a therapeutic target against CRPC." (PMID 36794010, 2023). "In addition, the analysis of “The Cancer Genome Atlas” (TCGA) database shows a lower expression of the E2-synthetizing enzymes HSD17B12 and HSD17B5 (also called AKR1C3) in tumour tissue samples compared to normal tissues for UCEC." (PMID 36674737, 2023). "Previous studies have shown that AKR1C3 promoted tumor proliferation and may be correlated with the phosphorylation of AKT." (PMID 35359392, 2022). "Thus, AKR1C3, as a key enzyme downstream of the androgen synthesis pathway in tumor cells, can be used as an effective target for the treatment of CRPC." (PMID 36591491, 2022). "Moreover, the cluster of EpCAM enriched cells were also enriched for several other genes of clinical interest including APOC1, a biomarker of tumor progression, ALDH1A1, a marker of tumor cell “stemness”, and AKR1C3, a marker of doxorubicin resistance." (PMID 33989287, 2021). "The mRNA and protein levels of AKR1C3 increased in HCC tumor tissues." (PMID 33493134, 2021). "In tumor tissue, AKR1C3 and AKR1D1 were secreted by HCC cells." (PMID 33493134, 2021).
tumor (continued). "We then analyzed whether CAF-induced upregulation of HMGCS2 and AKR1C3 was due to paracrine signaling between tumor cells and CAFs." (PMID 31980029, 2020). "Western blot analysis and IHC staining in xenograft tumour tissue confirmed that the expression of AR‐V7 protein was decreased in 22RV1 T sh564 xenografts after knocking down AKR1C3, linear regression confirmed positive correlation between AKR1C3 and AR‐V7." (PMID 32902124, 2020). "Based on the knowledge that inflammation is correlated with tumor development and progression in general, a dual inhibition of mPGES-1 and AKR1C3 might represent a promising point in action." (PMID 32731472, 2020). "Previous studies show that AKR1C3 has been upregulated in abiratarone resistant tumors, suggesting that, in the AR responsive phase, androgen biosynthesis is inhibited but that, in resistance phase, tumor cells acquire the capacity to overexpress AKR1C3 enzyme." (PMID 31638934, 2019). "Collectively, these results suggested that inhibition of AKR1C3 by indomethacin reduced radiation-resistant tumor growth, These results indicated that inhibition of AKR1C3 by indomethacin potentiated the cell killing effect of radiation.We used flow cytometry assay to dedect ROS." (PMID 27385003, 2016). "The present work demonstrates that AKR1B10, AKR1C1, AKR1C2 and AKR1C3 are transcriptional targets strongly indicative of NRF2 status in human tumours, and that NRF2 is the upstream effector of AKR overexpression in cancer, particularly in tumours of squamous origin." (PMID 27824809, 2016). "In the case of the mice with KY170R-scramble xenotransplants, irradiation led to a poor outcome: tumor growth was initially repressed upon irradiation but resumed within two weeks; extensive neoplasm and strong AKR1C3 expression was detected in the tumor tissues." (PMID 25419901, 2014). "Immunohistochemical staining analyses indicated that 7 (35%) of the radioresistant tumor specimens displayed high levels (+++, i.e.>75% tumor cells are AKR1C3 positive), and 8 (40%) displayed intermediate levels of AKR1C3 expression (++, i.e. 75%∼50% tumor cells contains AKR1C3 protein)." (PMID 25419901, 2014). "The elevated expression of AKR1C3 in tumor cells will maintain a reductive cellular environment, which not only leads to lower concentrations of ROS but may also be associated with chemoresistance." (PMID 25419901, 2014). "AKR1C3 acts as a switch controlling the response of tumor cells and the derived xenografts to IR." (PMID 25419901, 2014). "However, preliminary experiments showed that PR-104A metabolism and cytotoxicity is similar in cells from in vitro culture and from tumor xenografts despite slight apparent differences in AKR1C3 protein expression." (PMID 24109591, 2013). "On this basis, targeting tumour hypoxia and AKR1C3 is a promising approach to cancer therapy." (PMID 21982454, 2011). "Hence, further studies are required to determine how B/M and particularly MPA or other AKR1C3 inhibitors exert anti tumour activities in different tumour settings." (PMID 19997560, 2009). "In addition to the evidence found about the influence of the different subtypes of PGs on the distinct types of cancer, it is necessary to make special mention of the function of AKR1C3 protein that can determine the intensity of the effects of these lipid molecules on tumor development." (PMID 34199169, 2021). "Furthermore, we found that AKR1C3 overexpression could result in PCa DU145′s radioresistance,while the inhibition of AKR1C3 could restore the radiation sensitivity of the acquired tumor cells." (PMID 27385003, 2016). "Thus, the expression level of AKR1C3 in tumor cells might be useful as a biomarker for prediction of cellular radioresistance." (PMID 25419901, 2014). "AKR1C3 promoted EMT by regulating transcription factors and signaling pathways and led tumor cells to acquire more aggressive and metastatic characteristics of mesenchymal cells." (PMID 38523637, 2024).
tumor (continued). "AKR1C2 protein expression was correlated with survival outcomes in combination with clinicopathological data such as sex, HPV status, tumor status, smoking history, alcohol consumption, and protein expression levels of AKR1C1, AKR1C3, and NRF2." (PMID 39272833, 2024). "AKR1C3 is significantly upregulated in HCC and promotes tumor proliferation and metastasis through the activation of NF-κB signaling." (PMID 39834787, 2024). "Preclinical studies involving specific AKR1C3 prodrugs, such as AST-006 (TH-3424), have demonstrated cytotoxicity and anti-tumor activities against T-ALL cells in vitro and in vivo with AKR1C3 overexpression." (PMID 38523637, 2024). "5&6) AKR1C3 and AKR1B10 are enzymes that catalyzes redox transformation and play important role in tumor progression." (PMID 36959981, 2023). "Collectively, our data indicate that inhibition of AKR1C3 sensitized the resistant HCC cells to sorafenib by inducing LD breakdown and mitochondrial lipotoxicity in the xenograft tumor model of HCC." (PMID 36451864, 2022). "Several enzymes related to androgen biosynthesis and (re-)activation were highly expressed in all tumor biopsy samples, including HSD17B10, STS, SRD5A1, AKR1C3, and HSD11B2." (PMID 33974560, 2021). "For the orthotopic xenograft model, the metastatic tumor cells, particularly the liver and bone cells, possessed significantly higher expression levels of AKR1C1, AKR1C2 and AKR1C3, corresponding with increased cisplatin resistance." (PMID 27698389, 2016). "AKR1B10, AKR1C1, AKR1C2 and AKR1C3 constitute some of the most inducible targets of NRF2 in human systems, both normal and tumour-derived." (PMID 27824809, 2016). "Based on this communication, inter-relationships among AKR1C3, ER, IGF-1, Akt, and subsequent VEGF expression deserve further investigation for tumor angiogenesis and progression." (PMID 21134280, 2010). "Silencing ABCB1 or AKR1C3, or overexpressing LDHB, suppressed KIRC cell proliferation and migration in vitro; LDHB overexpression combined with sorafenib significantly reduced tumor growth in vivo." (PMID 40977852, 2025). "We further investigated contexts of these spMOCA’s hub genes, where we identified specific prognostic genes serves as hub genes in the same tumor type, for example, WIPF2 and CASC3 for BRCA, COX6A1 and PRAP1 for CRC, E2F1 and AKR1C3 for LUSC, and TSPAN3 and SLC4A11 for OVCA." (PMID 41370198, 2025). "As for PCA clusters, high Pearson correlation coefficients of gene expression within the cluster were only in case of AKR1C3, CBR1, CBR3 genes (r = 0.64 − 0.77, p-value < 0.05) in LUSC tumor as well as CBR1 and CBR3 (r = 0.72 − 0.86, p-value < 0.05) in ESCA tumor." (PMID 35453789, 2022). "Since both AKR1C3 and AKR1B10 were elevated in liver tumor tissues 50, an interplay between AKR1B10 and AKR1C3 by balancing FAO and glycolysis might be required to adapt to differential tumor environments and metabolic demands." (PMID 36451864, 2022). "Based on our observations that AKR1C3 and BCL7A have known functions in cancer and that ieQTLs in these genes are likely to be specific to tumor cells, we looked for other ieGenes across the datasets that may also play a role in cancer biology." (PMID 35725412, 2022). "The heatmap showed that more than half of the genes were downregulated in tumor tissue, and consistent with the univariate Cox regression analysis, they represented a better prognosis, including PTGS2, ACO1, DPP4, CRYAB, PRKCA, ACSL4 and AKR1C3." (PMID 34475496, 2021).
tumor (continued). "Notably, incubation of tumor cells with CAF-conditioned medium alone also resulted in an upregulation of HMGCS2 and AKR1C3 suggesting a paracrine communication between tumor epithelial cells and CAFs." (PMID 31980029, 2020). "AKR1C3 has recently been identified as a potential therapeutic target in both CRPC and ER-positive breast cancer, since it can promote intratumoral steroidogenesis to provide the hormones required for nuclear receptor activation and tumor progression." (PMID 24995161, 2014). "Moreover, AKR1C3 regulates and activates NF-κB by inducing autoubiquitination of TRAF6, subsequently releasing proinflammatory factors that enhance STAT3 phosphorylation, fostering increased tumor cell proliferation and invasion." (PMID 38523637, 2024). "To investigate whether AKR1C3-mediated LDs accumulation potentiates the vulnerability of sorafenib-resistant HCC cells, we examined the effect of the combined treatment of sorafenib with FLU on tumor growth in a xenograft model." (PMID 36451864, 2022). "Normal and tumour tissues from such patients were analysed by qRT-PCR for the following 12 genes; six from RNA-seq: CLDN1, MAGEB2, CD24, CEACAM6, IL1B and ISG15 and six from RNA-seq and proteomics cross-linking: AKR1C3, TNFAIP2, RAB7A, LGALS3BP, PSCA and SSRP1." (PMID 36428603, 2022). "In conclusion, expression of multifunctional AKR1C3, which is known to be the most up-regulated steroidogenic enzyme in patients with CRPC, might increase with the occurrence and longitudinal progression of the tumor in certain cases." (PMID 31052459, 2019). "It is noteworthy that bone metastases with ongoing bone formation showed higher tumor cell AKR1C3 immunoreactivity than cases without detectable bone formation, possibly due to intra-tumoral conversion of androstenedione to testosterone and subsequent osteoblast activation." (PMID 29670000, 2018). "Microarray and bioinformatics analysis suggested that overexpression of AKR1C3 in PC-3 cells modulates estrogen and androgen metabolism, activates insulin-like growth factor (IGF)-1 and Akt signaling pathways, as well as promotes tumor angiogenesis and aggressiveness." (PMID 21134280, 2010). "While mRNA levels of C3, AKR1C3, GAL3ST1 were not completely correlated with tumor pathological grades and stages." (PMID 37035174, 2023). "According to GEPIA in a GBM tumor, there is also increased expression of AKR1B1, decreased expression of AKR1C1 and AKR1C2, and no change in AKR1C3 expression." (PMID 36765904, 2023). "IHC results showed that the CAV1, AKR1C3, and TRIB3 protein expression levels were significantly higher in HNSCC tumor tissues (P < 0.05), but the difference in AURKA was not significant (P = 0.144)." (PMID 34539737, 2021). "After confirming that overexpression of AKR1C3 in HCT116 AKR1C3#6 did not modify the hypoxic fraction, we used the new HCT116 AKR1C3#6 clone to investigate the relationship between PR-104 activity and tumour oxygenation status." (PMID 34959631, 2021).